TNF (tumor necrosis factor)
Diseases named in the same sentence as TNF in open-access papers (continued):
Sharing a sentence is not in itself a finding about the gene and the disease.
periodontitis (continued). "We previously found that L-bLF given orally suppresses TNF-α production from mouse peripheral blood mononuclear cells (PBMCs); it also suppresses TNF-α expression in rat marginal periodontal tissue to a greater extent than non-liposomal bLF in LPS-induced experimental periodontitis." (PMID 40137863, 2025). "In wild‐type periodontitis mice, NAC‐S2 administration decreased the cemento‐enamel‐junction–alveolar bone crest (CEJ‐ABC) distance and the relative mRNA expression of TNF, IL‐6, and IL‐1β, while such phenomena could not be observed in TLR4 deficiency or Myd88 deficiency mice." (PMID 37647428, 2023). "Therefore, the primary aim of this preliminary study was to investigate GCF levels of IL-1β, IL-9, TNF-α, and VEGF before and after non-surgical periodontal treatment in patients suffering from stage III periodontitis with moderate and rapid rates of progression." (PMID 33218047, 2020). "In our study, inhibition of PTEN expression with siRNA results in upregulation of IL1 and TNF-α, whereas the expression of IL6 was not significantly altered, suggesting that PTEN may exert anti-inflammatory effects in mouse periodontitis by modulating the expression of IL1 and TNF-α." (PMID 31886238, 2019).
endothelial dysfunction (1,084 papers, 2005 to 2026). In vascular diseases, endothelial dysfunction is a systemic pathological state of the endothelium (the inner lining of blood vessels) and can be broadly defined as an imbalance between vasodilating and vasoconstricting substances produced by (or acting on) the endothelium. "This TNF-α-induced endothelial dysfunction is induced by the production of ROS, and it causes cell death via apoptosis through the activation of NF-κB." (PMID 40406487, 2025). "Studies have shown that PM2.5 exposure is associated with endothelial dysfunction and increased levels of pro-inflammatory cytokines such as IL-6 and TNF-α, which can exacerbate joint degeneration." (PMID 41170480, 2025). "Elevated levels of IL-1 and TNF-α have been particularly associated with endothelial dysfunction and the disruption of the blood–brain barrier, which in turn facilitates secondary neuronal injury and vasospasm." (PMID 40004783, 2025). "Studies suggest that inflammatory cytokines such as interleukin-6 and tumor necrosis factor-alpha contribute to endothelial dysfunction and platelet activation, thereby increasing thrombotic risk." (PMID 41301451, 2025). "Third, long-term screen time is connected to higher levels of inflammatory markers like interleukin (IL)-6 and tumor necrosis factor-alpha (TNF-α), which cause vascular inflammation, endothelial dysfunction, and high BP." (PMID 40182347, 2025). "A number of studies have shown that excessive production of TNF-α in the placenta and peripheral blood is associated with endothelial dysfunction and increased vascular tone." (PMID 41463130, 2025). "Infection induces a pro-inflammatory environment characterized by cytokine release (e.g., IL-6, TNF-α), which recruits immune cells but also contributes to endothelial dysfunction by increasing permeability and causing vascular damage." (PMID 40141288, 2025). "Systemic inflammation marked by elevated levels of CRP, TNF-α, and IL-6 has been linked to increased vascular stiffness and endothelial dysfunction, which tend to elevate systolic pressure more than diastolic." (PMID 40584971, 2025). "IL-6 and TNF-α contribute to cardiovascular risk by promoting endothelial dysfunction, oxidative stress, and vascular remodeling." (PMID 40552192, 2025). "This antagonism suppresses the production of pro-inflammatory cytokines like TNF-α and IL-6, which are implicated in endothelial dysfunction and vascular impairment associated with ED." (PMID 40005617, 2025). "Elevated TNF-α levels have been associated with endothelial dysfunction in hypertension, increased carotid intima-media thickness, and greater CAD risk, and have been shown to promote foam cell formation via monocyte activation." (PMID 41155389, 2025). "Stronger evidence supports the role of periodontal inflammation and oral microbiota dysbiosis in systemic inflammatory burden, with elevated mediators such as CRP, IL-6, TNF-α, and IL-1β implicated in endothelial dysfunction and atherogenesis." (PMID 41294894, 2025). "Multiple systemic vascular inflammatory disorders are associated with endothelial dysfunction and elevated levels of TNFα and IFNγ." (PMID 40894883, 2025). "Key proinflammatory cytokines, including Tumor Necrosis Factor- Alpha (TNF-α), Interleukin (IL) IL-6, and IL-17, contribute to endothelial dysfunction and oxidative stress, exacerbating cardiovascular risk." (PMID 40937212, 2025). "Elevated levels of IL-6 correlate with increased myocardial injury and worse clinical outcomes, while TNF-α and IL-1β have been implicated in endothelial dysfunction, smooth muscle proliferation, and cardiac fibrosis." (PMID 40724554, 2025). "TNF-α stimulation increased NF-κB-dependent miR-214-3p expression in endothelial cells, impairing eNOS expression and causing endothelial dysfunction." (PMID 38825645, 2024).
endothelial dysfunction (continued). "Activation of NF-κB and NLRP3 inflammasome is associated with production of tumor necrosis factor-alpha (TNF-α), IL-1β, and IL-6 inflammatory cytokines leading to vascular damage, endothelial dysfunction resulting in hypertension and cardiovascular disease." (PMID 39081863, 2024). "Inflammatory substances such as TNF-α suppress the eNOS gene expression in endothelial cells, causing endothelial dysfunction and subsequently leading to erectile dysfunction." (PMID 38741154, 2024). "Treatment with anti TNF-α medication improves the microvascular endothelial dysfunction, reducing the cardiovascular risk in these patients." (PMID 39337413, 2024). "The G/G genotype at the −308 position is more frequent in preeclamptic women and is associated with higher TNF-alpha expression, promoting inflammation and endothelial dysfunction." (PMID 39062815, 2024). "TNF-α, in turn, induces the production of reactive oxygen species which determines further damage to the endothelial cells, causing endothelial dysfunction and inflammation." (PMID 37500944, 2024). "Given the observation that soluble fms-like tyrosine kinase (sFlt)-1 and tumour necrosis factor (TNF)α are implicated in the endothelial dysfunction associated with preeclampsia, we investigated their effect on cultured normotensive term omental arteries." (PMID 37047162, 2023). "Increased TNF-α levels in patients and HVs with vascular risk factors strongly support the involvement of this cytokine in endothelial dysfunction, a prominent cause of BBB permeability." (PMID 36056287, 2023). "Taken together, these results indicate that GYY4137 enhances intracellular H2S content and TNF-α cause endothelial dysfunction in HUVECs." (PMID 36978982, 2023). "Elevated levels of IL-1β and TNF-α have been associated with endothelial dysfunction and contribute to the pathogenesis of IRI." (PMID 37675177, 2023). "A new type of RA treatment that includes anti-TNF therapy has been shown to reduce the risk of endothelial dysfunction." (PMID 37987275, 2023). "Vitamin D also reduces the risk of endothelial dysfunction by inhibiting other proinflammatory factors such as TNF-alpha and IL-6, which reduce the availability of NO and the activity of eNOS." (PMID 38068901, 2023). "MR-proADM also showed a strong correlation with systemic inflammation markers such as CRP, IL6, and TNFα, as well as significant associations with endothelial dysfunction biomarkers (SDMA, ADMA, and C-CTproET1)." (PMID 37626802, 2023). "TNFα plays a pivotal role in endothelial dysfunction through the disturbance it causes to the equilibrium between endothelial nitric oxide synthase (eNOS) and inducible nitric oxide synthase (iNOS) activities, which results in pro-apoptotic NO activity." (PMID 36362055, 2022). "This prothrombotic state is possibly related to the increase in inflammatory cytokine levels (high sensitivity C-reactive protein (CRP), IL-6 and TNF-α), which are proatherogenic, decrease endothelial progenitor cell survival and cause endothelial dysfunction." (PMID 35207718, 2022). "An animal experiment showed that perirenal fat directly causes renal artery endothelial dysfunction, which was partly mediated by tumor necrosis factor-α." (PMID 36014894, 2022). "The main mechanisms implicated in TNF-α-induced atherogenesis are endothelial dysfunction, oxidative stress, and VSMC secretory phenotype promotion." (PMID 36555579, 2022). "Another study showed that the administration of a high-fat meal resulted in an increase in tumor necrosis factor alpha (TNF-α), a cytokine that is associated with endothelial dysfunction." (PMID 35744087, 2022). "Increased levels of proinflammatory cytokines such as tumor necrosis factor (TNF), interferon-gamma, and interleukin 1 (IL-1) have been linked to aging-related endothelial dysfunction." (PMID 35783193, 2022).
endothelial dysfunction (continued). "Its activation in the diabetic heart causes the release of interleukins and TNF-α and amplifies oxidative stress resulting in endothelial dysfunction in T2D." (PMID 34497520, 2021). "AKI is known to cause increased plasma levels of inflammatory mediators including tumor necrosis factor alpha, interleukins 1 and 6, and interferon-γ, causing systemic inflammation, oxidative stress, and endothelial dysfunction." (PMID 33398648, 2021). "The pro-inflammatory cytokine tumor necrosis factor (TNF)-α, produced in excess in RA, causes the release of adhesion molecules and is one factor that drives endothelial dysfunction." (PMID 35056068, 2021). "The critical roles of cytokines and NF-κB pathway in mediating dysfunctions of HUVECs were supported by the fact that the proinflammatory cytokines like TNF-α activate NF-κB pathway and cause endothelial dysfunction in patients." (PMID 33536546, 2021). "In clinical studies, increased TNF-α circulating levels were found to be associated with the endothelial dysfunction in hypertensive patients; with carotid atherosclerosis thickness in patients with early atherosclerosis and with CAD risk." (PMID 33917744, 2021). "Previous studies from our lab suggest that CysLTR signaling causes endothelial dysfunction and potentiates the attachment of monocytes to EC in response to TNFα." (PMID 34867460, 2021). "In aged rats, there is an increase in the blood level of TNF-α, which is associated with endothelial dysfunction of coronary arteries, whereas chronic inhibition of TNF-α improves the slowing of blood flow in mesenteric arteries of the aged rats." (PMID 32121175, 2020). "TNF-α dependent Endothelial dysfunction in type II diabetes was linked to over production of ROS and a decrease in NO bioavailability." (PMID 32426041, 2020). "TNF-α has been known to elicit endothelial dysfunction associated with hypertension through the downregulation of eNOS by upregulating NF-κB-responsive miR-31-5p and miR-155-5p." (PMID 32878300, 2020). "In summary, using genetic model of TNFα deficiency, we demonstrate that inflammatory cytokine TNFα plays a critical role in endothelial dysfunction and cardiac and vascular injury in DOCA/salt hypertension." (PMID 32190663, 2020). "In the present study, we investigated the role of TNFα in endothelial dysfunction and cardiovascular injury using TNFα-deficient mice in DOCA/salt hypertension." (PMID 32190663, 2020). "Elevation of TNF-α and IL-6 expression are linked to increased oxidative stress, endothelial dysfunction and renal fibrosis." (PMID 32292787, 2020). "We have previously shown that salt-sensitive hypertension has severe endothelial dysfunction and end organ damage, which are linked to the activation of the NFκB inflammatory pathway and increased vascular TNFα expression." (PMID 32190663, 2020). "IL-6 is involved in systemic features of COPD, such as muscle weakness and endothelial dysfunction, while TNF-α is usually associated with airway inflammation through activation of the nuclear factor kappa B pathway." (PMID 31191356, 2019). "Evidence suggests that increased TNF-α and CD-40 ligand are linked to endothelial dysfunction and subsequent atherogenesis with late thrombotic complications." (PMID 31244668, 2019). "Pro-inflammatory stimuli, including LPS and TNF-α, usually cause endothelial dysfunction, leading to the initiation of inflammatory responses in numerous cardiovascular diseases." (PMID 31375092, 2019). "TNF-α and IL-6 are inflammatory cytokines, released from peri-visceral fat and found to be associated with IR, endothelial dysfunction and atherogenesis." (PMID 30635365, 2019). "Activation of nuclear factor-κB (NF-κB) is indispensable for the stimulation of vascular TNF-α production and adhesion molecules, causing endothelial dysfunction under various pathological factors." (PMID 30577658, 2018).
endothelial dysfunction (continued). "In order to better understand the molecular mechanisms underlying inflammatory endothelial dysfunction, we examined the effects of SelS on TNF-α-induced HUVECs dysfunction." (PMID 29805311, 2018). "Taken together, the findings indicated that the presence of IL-6 or TNF-α in diabetic mice was associated with the reduced phosphorylation of eNOS-mediated endothelial dysfunction." (PMID 29095915, 2017). "Inflammatory cytokines can target vascular endothelium to induce endothelial dysfunction, for example, TNFα has been shown to induce endothelial dysfunction associated with increased oxidative stress and decreased eNOS expression." (PMID 29236702, 2017). "DKK-1 is linked not only with the effects of TNFα on joints in RA but also with platelet-mediated endothelial cell activation, endothelial dysfunction in T2DM, vascular calcification, and premature myocardial infarction." (PMID 28553649, 2017). "In our preclinical cirrhosis models, serelaxin decreased the (elevated) serum levels of TNFα, a pro-inflammatory cytokine heavily implicated in endothelial dysfunction." (PMID 28245243, 2017). "Jee & Jin (2012) also demonstrated increased endothelial dysfunction markers, mainly sE-selectin, which was associated with leukocyte trafficking, exercise intensity, TNF-α, CRP, and CK." (PMID 27911915, 2016). "Elevated concentrations of interleukin-6 (IL-6), tumor necrosis factor (TNF-α) and other inflammatory cytokines in plasma have been shown to be linked to endothelial dysfunction in obese patients." (PMID 27250532, 2016). "The increasing concentration of TNF-α led to an increase in reactive oxygen species that caused endothelial dysfunction." (PMID 27619170, 2016). "Visceral fat is associated with carotid atherosclerosis contributing to endothelial dysfunction through the direct effect of mainly adiponectin and TNF-α, both secreted after macrophage recruitment through MCP-1." (PMID 26580647, 2015). "This leads to the release of histamine, which then diffuse from the adventitia to the intima and enhances the endothelial dysfunction caused by TNF-α from activated intimal macrophages." (PMID 25811595, 2015). "Inflammatory cytokines such as TNF-α are master regulators of vascular proatherogenic changes, which has been linked to endothelial dysfunction in many pathophysiological conditions." (PMID 25162582, 2014). "EAT has various endocrine and inflammatory functions and produce mediators such as interleukin-6, interleukin-1b, tumor necrosis factor-α and monocyte chemotactic protein-1, which can cause endothelial dysfunction." (PMID 24872849, 2014). "Endothelial dysfunction is seen as a major pathogenic factor in RA-associated cardiovascular morbidity with an important role for TNF-α." (PMID 24620738, 2014). "Oxidative stress and the proinflammatory cytokine tumor necrosis factor-α contribute to endothelial dysfunction and large artery stiffening in estrogen-deficient postmenopausal women." (PMID 25984561, 2014). "Using genetic tools to manipulate TNF-α expression in the mouse, it was found that myocardial ischemia-reperfusion evokes superoxide-dependent endothelial dysfunction and NO deficiency via upregulation of Arg-I, in a manner correlating with TNF-α expression." (PMID 23966996, 2013). "In this study, we provide further insight into the cellular mechanisms mediating endothelial dysfunction, by showing that the stress-sensor protein p66Shc is implicated in TNFα action in HUVEC, a well-defined cellular model of the human endothelium." (PMID 24349153, 2013). "TNFα causes endothelial dysfunction by various mechanisms that includes activation of transcription factor NF-κB." (PMID 18691416, 2008). "TNFα is one of the major proinflammatory cytokines that causes endothelial dysfunction by various mechanisms including activation of transcription factor NF-κB, a key transcription factor that regulates expression of CAMs." (PMID 18691416, 2008).